EZH2 (enhancer of zeste 2 polycomb repressive complex 2 subunit)
Diseases named in the same sentence as EZH2 in open-access papers (continued):
Sharing a sentence is not in itself a finding about the gene and the disease.
myocardial infarction (9 papers, 2018 to 2025). Gross necrosis of the myocardium, as a result of interruption of the blood supply to the area, as in coronary thrombosis. "NOTCH1 signaling influences DLBCL development and myocardial infarction severity through the EZH2/STAT3 pathway, leading to increased heart fibrosis." (PMID 39951437, 2025). "a DLBCL mouse model was created by lentivirus-mediated knockdown of NOTCH1 and EZH2 genes, followed by myocardial infarction induction." (PMID 39951437, 2025). "EZH2 inhibitor GSK-343 enhances human mononuclear cell reparative function post-myocardial infarction, thereby preventing infarct size expansion and cardiac dysfunction, by resolving H3K27 methylation and promoting inflammation resolution." (PMID 38994197, 2024). "In this study, the authors show that Ezh2 pharmacological inhibition, acting as an epigenetic checkpoint in monocytes and macrophages, prevents myocardial infarction-induced cardiac dysfunction." (PMID 37491334, 2023). "Heart tissue from mice with myocardial infarction, like tissue from patients with ischemic heart disease, showed increased EZH2 and H3K27me3, as well as reduced Na+ channel (Nav1.5) expression." (PMID 37504561, 2023). "We constructed a ceRNA network based on our lncRNA microarray data and validated the correlation between myocardial infarction-associated transcript lncRNA (MIAT), miRNA-150-5p, and EZH2 in vitro and in vivo." (PMID 34811354, 2021). "Ezh2 deficiency in cardiomyocytes did not affect clearance of the fibrotic scar in myocardial infarction (MI) and apical resection models of cardiac injury at post-natal day 1 (P1)." (PMID 29466371, 2018). "In this study, NOTCH1 was found to suppress EZH2 gene expression, impacting DLBCL tumorigenicity and myocardial infarction extent." (PMID 39951437, 2025). "We aim to investigate the exacerbation of cardiac fibrosis by studying the effects of the NOTCH1 signaling pathway through EZH2-induced excessive methylation, resulting in the production of GM-CSF and IL-6, while establishing an animal model of DLBCL with an additional myocardial infarction model." (PMID 39951437, 2025). "We show that inactivation of Ezh2 and decreasing the global levels of H3K27me3 in CMs does not affect the regenerative response of the neonatal heart after myocardial infarction or apical resection." (PMID 29466371, 2018). "However, Ezh1, but not Ezh2, was required for regeneration following myocardial infarction, i.e., injury, in mice." (PMID 37504561, 2023).
osteoarthritis (9 papers, 2016 to 2025). A noninflammatory degenerative joint disease occurring chiefly in older persons, characterized by degeneration of the articular cartilage, hypertrophy of bone at the margins and changes in the synovial membrane. "This is significant as EZH2 has been shown to upregulate β-catenin in an osteoarthritis model, causing increased collagen deposition." (PMID 41282610, 2025). "Alternatively, the methyltransferase activity of EZH2 could be inhibited to offset the loss of KDM6B-mediated H3K27 demethylation in osteoarthritis." (PMID 35915507, 2022). "Histone methyltransferase EZH2 is upregulated during osteoarthritis (OA), which is the most widespread rheumatic disease worldwide, and a leading cause of disability." (PMID 33177650, 2020). "The development of osteoarthritis was ameliorated by inhibition of EZH2 through the Wnt/β-catenin pathway." (PMID 30086750, 2018). "3-Deazaneplanocin A (DZNep) is an inhibitor of S-Adenosyl-L-Homocysteine Hydrolase (SAHH) known to inhibit EZH2, a histone methylase upregulated during osteoarthritis." (PMID 28744016, 2017). "The purpose of our study was to elucidate the role of the histone methyltransferase enhancer of zeste homologue 2 (EZH2) in the pathophysiology of osteoarthritis (OA) and to develop a strategy to modulate EZH2 activity for OA treatment." (PMID 27539752, 2016). "EZH2, a histone methyltransferase enhancer, was overexpressed in RA synovial fibroblasts (SF) compared with osteoarthritis (OA) SF." (PMID 27042192, 2016). "Indeed, EZH2 inhibition with the inhibitor EPZ-6438 attenuated disease progression in mice with DMM-induced osteoarthritis." (PMID 35915507, 2022). "Together, these studies demonstrate the importance of H3K27me3 regulation in metabolism of chondrocytes, and osteoarthritis process, and suggest that the histone methyltransferase EZH2 could be an appropriate target to reduce OA progression." (PMID 33177650, 2020). "However, one study suggests on the contrary, that conditional knockout of EZH2 aggravates osteoarthritis development." (PMID 33177650, 2020). "Our results indicate that developing a specific inhibitor of EZH2 may be beneficial for the prevention or therapeutic treatment of osteoarthritis." (PMID 27539752, 2016). "Interestingly, we also found the upregulation level of EZH2 expression with increased H3K27me3 level in 2-year-old natural-aging mice, suggesting the changes in EZH2 lead to the increase in H3K27me3 during the development of osteoarthritis." (PMID 37217512, 2023). "Pharmacological inhibition of EZH2 may be an effective therapeutic approach for osteoarthritis." (PMID 27539752, 2016).
ovarian clear cell cancer (9 papers, 2016 to 2023). An invasive malignant neoplasm that arises from the ovary and is characterized by a predominance of clear and hobnail malignant epithelial cells. "Notably, inhibition of EZH2 has been suggested as a treatment for ARID1A-deficient ovarian clear cell carcinoma through a synthetic lethal relationship with ARID1A." (PMID 35326450, 2022). "For instance, SNHG6 can promote the progression of colorectal and ovarian clear cell carcinomas by regulating the expression of enhancer of zeste homolog 2 (EZH2) through a ceRNA network." (PMID 37004005, 2023). "The therapeutic utility of EZH2 has been explored extensively in ovarian clear-cell cancer (OCCC), another gynecologic cancer with high rates of ARID1A mutation." (PMID 35326450, 2022).
Peritoneal Fibrosis (9 papers, 2021 to 2026). Disorder characterized by a wide range of structural changes in PERITONEUM, resulting from fibrogenic or inflammatory processes. "Combining these findings, we found that EZH2 regulated lipid deposition, peritoneal fibrosis, and EMT mediated by klotho." (PMID 36724065, 2023). "The vital effect of EZH2 in PD-related peritoneal fibrosis has been expounded on in our previous research." (PMID 36724065, 2023). "It was discovered that EZH2 has a role in repressing Smad7 to enable activation of fibrotic genes in cardiac, kidney, and peritoneal fibrosis." (PMID 37476157, 2023). "In vivo experiments have also revealed that GSK343 (enhancer of zeste 2 polycomb repressive complex 2 subunit (EZH2) inhibitor) could relieve peritoneal fibrosis, lipid deposition, and EMT by mitigating EZH2 and restoring klotho expression." (PMID 38390449, 2024). "Overall, our study revealed that EZH2 plays a vital role in peritoneal fibrosis." (PMID 36724065, 2023). "To reveal whether EZH2 and klotho are involved in the pathogenesis of PD-related peritoneal fibrosis, we examined their expression in HPMCs treated with different concentrations of glucose for 48 h." (PMID 36724065, 2023). "Moreover, inhibition therapy targeting EZH2 in both models alleviated peritoneal fibrosis and suppressed the activation of various pro-fibrotic signaling pathways, such as TGF-β1/Smad3, Notch1, EGFR, and Src, as well as phosphorylation events involving STAT3 and NF-κB." (PMID 39749340, 2024). "However the detailed mechanism of EZH2 and klotho in peritoneal fibrosis remained unclear." (PMID 36724065, 2023). "Hence, EZH2 and klotho could act as potential targets for the treatment of peritoneal fibrosis." (PMID 36724065, 2023). "Administration of 3-deazaneplanocin A (3-DZNeP) in mouse models of CG- or HG-PDF-induced peritoneal fibrosis has been shown to mitigate peritoneal injury by reducing CD68+ macrophage invasion and angiogenesis through the inhibition of EZH2 methylation activity." (PMID 39749340, 2024). "In vivo experiments also revealed that GSK343 could relieve peritoneal fibrosis, lipid deposition and EMT by mitigating EZH2 and restoring klotho expression." (PMID 36724065, 2023). "GSK343 (enhancer of zeste 2 polycomb repressive complex 2 subunit (EZH2) inhibitor) has been verified to inhibit epithelial mesenchymal transdifferentiation (EMT) and peritoneal fibrosis, but its related mechanism remains unclear." (PMID 36724065, 2023). "Two inhibitors of EZH2 HMT activity, 3-Deazaneplanocin A (DZNep) and GSK126, can preserve Smad7 expression to significantly prevent UUO-induced kidney fibrosis, transverse aortic constriction surgery-induced cardiac fibrosis in mice, and a mouse model of peritoneal fibrosis." (PMID 37476157, 2023).
rectal cancer (9 papers, 2009 to 2025). A primary or metastatic malignant neoplasm that affects the rectum. "EZH2 was found in high concentrations in normal rectal tissues and in varying high and medium concentrations in rectal cancer tissues." (PMID 40770782, 2025). "Our findings reveal that EZH2 is substantially expressed in rectal cancer tissues, which is consistent with the findings of other solid tumor studies." (PMID 40770782, 2025). "Preoperative identification of EZH2 protein expression in tumor tissues in patients with locally advanced rectal cancer can screen out the group with a higher likelihood of benefit from neoadjuvant chemotherapy." (PMID 40770782, 2025). "Thus, mixed groups of colon and rectal cancer can strongly influence the prognostic value of EZH2 expression." (PMID 31317325, 2019). "However this is a relatively small retrospective study, to further validate the role of EZH2 in rectal cancer, large consistent cohort studies are needed." (PMID 25159232, 2014). "Comparatively, SNHG1 was found to promote initiation and metastasis of rectal cancer through regulating let-7b-5p/ATP6V1F and miR-423-5p/EZH2 axes, respectively." (PMID 33194594, 2020). "This article investigated whether Runt-Related Transcription Factor 3 (RUNX3) and enhancer of zeste homolog 2 (EZH2) can be used to evaluate the clinical efficacy of neoadjuvant therapy and prognosis of locally advanced rectal cancer (LARC)." (PMID 35280723, 2022).
chondrosarcoma (8 papers, 2014 to 2023). A malignant cartilaginous matrix-producing mesenchymal neoplasm arising from the bone and soft tissue. "Many studies have shown that HOTAIR is physically associated with EZH2.34, 35, 36 In our study, EZH2 was upregulated in both chondrosarcoma cells and specimens, and knockdown of HOTAIR led to repression of EZH2." (PMID 28182000, 2017). "The potential use of EZH2 expression for improving diagnostic of chondrosarcomas and the correlation between its expression and tumor grade or prognostic for patients is still in process." (PMID 24852755, 2014). "To validate the role of EZH2 in tumorigenicity of chondrosarcoma, we introduced shEZH2 or control shRNA by lentiviral system into chondrosarcoma cell lines." (PMID 36622753, 2023). "We first searched the genes that were both targeted by EZH2 (n=704) and associated with significant dysregulated genes from cDNA microarray in comparison with normal chondrocyte to JJ012 chondrosarcoma cell line (n=6771)." (PMID 36622753, 2023). "Here, we identify a signal pathway way involving EZH2/SULF1/cMET axis that contributes to malignancy of chondrosarcoma and provides a potential therapeutic option for the disease." (PMID 36622753, 2023). "q-ChIP experiments further validated enrichment of EZH2 bound at Sulf1 promoter in various chondrosarcoma cell lines." (PMID 36622753, 2023). "Targeting EZH2/SULF1/cMET shown in this report provides proof of concept evidence to use cMET as biomarker to select chondrosarcoma patients for treatment by the FDA-approved cMET inhibitors such as crizotinib." (PMID 36622753, 2023). "Here, we reported that expression of EZH2 was augmented in chondrosarcoma cell lines, which exerted a critical role in tumor progression." (PMID 36622753, 2023). "A non-biased chromatin immunoprecipitation sequence, cDNA microarray analysis, and validation of chondrosarcoma cell lines identified sulfatase 1 (SULF1) as the top EZH2-targeted gene to regulate chondrosarcoma progression." (PMID 36622753, 2023). "To examine the potential role of EZH2 in chondrosarcoma malignancy, we initially conducted western blot to analyze the expression of EZH2 in normal chondrocytes and chondrosarcoma cell lines." (PMID 36622753, 2023). "To identify EZH2-targeted genes in chondrosarcoma, we used cDNA microarray and EZH2-ChIP sequencing (ChIP-seq) profiling to identify the dysregulated genes which were targeted by EZH2 in chondrosarcoma cell lines." (PMID 36622753, 2023). "The compound, DZNep, was shown to attenuate EZH2 protein expression and subsequently decreased H3K27me3, resulted in promoting cell death of chondrosarcoma cell line by apoptosis." (PMID 36622753, 2023). "Using pharmaceutical inhibitors targeting at EZH2 or cMET to treat chondrosarcoma mice model significantly reduced tumor growth and prolonged mice survival." (PMID 36622753, 2023). "The phosphorylation of cMET was vigorously decreased while depletion of EZH2 in chondrosarcoma cell line." (PMID 36622753, 2023). "It seems that the FDA-approved cMET inhibitors showed more potent retardation on chondrosarcoma tumorigenesis than inhibition of currently available EZH2 inhibitors." (PMID 36622753, 2023). "Overexpressed EZH2 resulted in downregulation of SULF1 in chondrosarcoma cell lines, which in turn activated cMET pathway." (PMID 36622753, 2023). "All these results revealed that SULF1 is a downstream target of EZH2 and serves as a tumor suppressor role in chondrosarcoma development." (PMID 36622753, 2023). "In contrast, we observed the inhibition of SULF1 expression through histone 3 K27 trimethylation by EZH2 to attenuate the elimination of 6-O-sulfation in chondrosarcoma, resulting in the high level of 6-O-sulfation of HSPGs to enhance RTK signaling like cMET." (PMID 36622753, 2023).
chondrosarcoma (continued). "In this study, we integrated EZH2-chromatin immunoprecipitation (ChIP) sequence and cDNA microarray analysis then validated in multiple chondrosarcoma cell lines to identify SULF1 as a top EZH2-targeted gene governing chondrosarcoma progression." (PMID 36622753, 2023). "EZH2 chromatin immunoprecipitation sequencing (ChIP-seq) was conducted in JJ012 chondrosarcoma cell line." (PMID 36622753, 2023). "We demonstrated that EZH2/SULF1 axis mediates cMET in chondrosarcoma, and inhibition of cMET at low dose for long-term administration effectively alleviates tumor growth of chondrosarcoma and prolongs survival in mice." (PMID 36622753, 2023). "The regulation of EZH2/SULF1/cMET axis were further validated in patient samples with chondrosarcoma." (PMID 36622753, 2023). "In chondrosarcoma, the expression of EZH2 was upregulated and thereby inhibited the SULF1 expression." (PMID 36622753, 2023). "Venn diagram showing the overlap between genes (n=40) differentially dysregulated from cDNA microarray in chondrosarcoma cells compared to normal chondrocyte (n=6761) and genes targeted by EZH2 from EZH2 ChIP-seq in chondrosarcoma (n=704)." (PMID 36622753, 2023). "The significance of methyltransferases other than H3K27 methyltransferase of EZH2 has been shown in chondrosarcoma cell lines." (PMID 35008205, 2021). "To ascertain the association among KLF6, EZH2, SP1, and SNHG6 during the progression of chondrosarcoma, we then measured the expression of EZH2 and SP1 in KLF6-overexpressing SW1353 and HCS2/8 cells." (PMID 33431838, 2021). "In the present study, we for the first time found that SP1 induced the upregulation of SNHG6, which then led to the suppression of KLF6 by recruiting EZH2 and promoted the tumorigenesis of chondrosarcoma." (PMID 33431838, 2021). "SNHG6 suppressed the transcription of tumor-suppressor gene KLF6 through EZH2, which further promoted the tumorigenesis of chondrosarcoma." (PMID 33431838, 2021). "As expected, DZNep treatment reduced EZH2 protein level, and subsequently H3K27me3 level in two chondrosarcoma cell lines, CH2879 and SW1353." (PMID 24852755, 2014). "Here, we show that high grade chondrosarcomas express EZH2 protein, and that DZNep reduces its expression and subsequently H3K27me3." (PMID 24852755, 2014). "Here, we identified, 3-Deazaneplanocin A (DZNep), a small molecule EZH2 inhibitor, as a putative treatment of chondrosarcomas." (PMID 24852755, 2014). "Immunohistochemistry analysis from patient biopsies showed that EZH2 is expressed in nucleus of high grade chondrosarcomas (for 6/7 samples)." (PMID 24852755, 2014). "We also tested whether the loss of EZH2, which induces SULF1 expression, would impair cMET phosphorylation in chondrosarcoma cell lines." (PMID 36622753, 2023). "(D) A propose model of the regulation of EZH2/SULF1/cMET axis in chondrosarcoma." (PMID 36622753, 2023). "We, therefore, determined whether pharmacological inhibition of EZH2 or cMET activity could be an option for target therapy for chondrosarcoma." (PMID 36622753, 2023). "SULF1 is the downstream targeted of EZH2 and repressed in chondrosarcoma cell lines." (PMID 36622753, 2023). "Pathological relevance of EZH2/SULF1/cMET axis in chondrosarcoma." (PMID 36622753, 2023). "The results indicated that SULF1 is the direct targeted gene of EZH2 in chondrosarcoma cell lines." (PMID 36622753, 2023). "EZH2 inhibited microRNA-454-3p (miR-454-3p) by binding to its promoter in chondrosarcoma cells." (PMID 33363140, 2020). "Interestingly, a previous study has elucidated that when EZH2 is recruited into the microRNA-454-3p (miR-454-3p) promoter regions, DNA methylation of miR-454-3p is induced to downregulate miR-454-3p in chondrosarcoma cells." (PMID 33363140, 2020). "Furthermore, by Western-Blot, we found that EZH2 expression was higher in chondrosarcoma cells than normal chondrocytes." (PMID 24852755, 2014).